REN (renin)
Diseases named in the same sentence as REN in open-access papers (continued):
Sharing a sentence is not in itself a finding about the gene and the disease.
preeclampsia (continued). "Furthermore, among the preeclampsia women, active renin and autoantibodies influence the receptor of Angiotensin II type 1, which then raise the systemic blood pressure." (PMID 41536823, 2025). "In preeclampsia, the renin-angiotensin system (RAS) exhibits suppression." (PMID 41287642, 2025). "Given the likely role of the renin-angiotensin system in the vascular pathology of preeclampsia, it possible this drug could be effective in treating preeclampsia." (PMID 40497429, 2025). "Women with preeclampsia had reduced placental and urinary Na+ concentrations, yet increased urinary angiotensinogen and reduced active renin, aldosterone concentrations, and osmotic response signal TonEBP (tonicity-responsive enhancer binding protein) expression." (PMID 38966986, 2024). "Since low blood Ca2+ levels stimulate the production of renin and parathyroid hormones, which increase intracellular Ca2+ in vascular smooth muscle, blood Ca2+ levels appear to be critical in the pathophysiology of preeclampsia." (PMID 39314616, 2024). "The dysregulation of the renin-angiotensin system (RAS) may participate in the pathogenesis of preeclampsia." (PMID 36833689, 2023). "There was not an apparent association among gestational hypertension and elevated aldosterone concentrations or declining renin activity." (PMID 38001956, 2023). "Additionally, most currently available therapeutic inhibitors of renin-angiotensin-aldosterone system are teratogenic and fetotoxic, precluding their use to treat preeclampsia." (PMID 37089425, 2023). "Previous studies by our lab and others have reported that gestational hypertension and/or pre-eclampsia is accompanied by attenuated renin activity and lower aldosterone concentrations compared to normotensive pregnancies, presumably reflecting a response to increased systemic vascular resistance." (PMID 38001956, 2023). "However, the results of investigations on the significance of the renin-angiotensin system in gestational diabetes and preeclampsia have been contentious." (PMID 35309508, 2022). "These may imply a time-dependent activation/suppression of the renal renin-angiotensin system during preeclampsia, as measured by urine angiotensinogen/creatinine levels." (PMID 35309508, 2022). "Thus, we demonstrated the possibility of the synthesis of the key metabolites of the renin–angiotensin–aldosterone system by the placenta, with an increase in their level in the placental structures in preeclampsia." (PMID 36580212, 2022). "Our study supports the implications of these previous studies, that chronic stress-induced decidual NRF2 activation might be a detrimental step in the development of preeclampsia potentially resulting in FGR through its effect on the renin–angiotensin system." (PMID 35216082, 2022). "Renin-angiotensin system has been involved in the development of preeclampsia." (PMID 35309508, 2022). "Indeed, a recent study identified renin as the most upregulated gene in human extravillous cytotrophoblasts from severe preeclampsia cases." (PMID 33301424, 2021). "Renin and Ang II levels are depressed in the plasma of women with preeclampsia." (PMID 31551925, 2019). "Involvement of the renin–angiotensin system in the pathogenesis of preeclampsia has been suggested." (PMID 25716926, 2015). "Renin-angiotensin signaling was found predominantly in preterm preeclampsia in our study, while the previous reports show this deranging systemic endothelial function occurs in both preterm and term preeclampsia." (PMID 25392996, 2014). "In contrast, the child's REN haplotypes A-t-C and c-G-t did not affect the mother's risk of preeclampsia, and neither did the child's AGT haplotypes C-T-A, C-c-g or t-c-g (data not shown)." (PMID 20537141, 2010). "Overall, the mother's REN haplotypes did not affect her risk of developing preeclampsia (data not shown)." (PMID 20537141, 2010).
preeclampsia (continued). "Except for a borderline-significant double-dose effect of one of the haplotypes, fetal REN haplotypes did not appear to influence the mother's risk of preeclampsia." (PMID 20537141, 2010). "The paradox between overexpression of renin and angiotensinogen creating preeclampsia-like symptoms in mice and the reduced levels observed in humans with preeclampsia suggests that renin-angiotensin-aldosterone system may be a downstream effect of other dysregulated systems." (PMID 37089425, 2023). "Although, the peripheral RAS (plasma levels of active renin, renin and Ang II) is downregulated in the DOCA preeclampsia model; the association of gene polymorphisms of RAS and preeclampsia was observed in human, moreover, T allele of angiotensinogen may involve in the pathogenesis of PE." (PMID 29085302, 2017). "Therefore, our objective was to determine whether the genes for placental renin (REN) and maternal angiotensinogen (AGT) interact to influence the risk of preeclampsia." (PMID 20537141, 2010). "In preeclampsia, a dysregulated RAS is considered to play a key role in pathogenesis by release of placental renin, other RAS proteins, and miRNA." (PMID 35860693, 2022). "The most relevant targets for preeclampsia were: AR, VDR, SLC6A2, NOS3 and CHRM4, while ABCG2, ERBB2, CES1 and REN led to the most relevant off-targets." (PMID 33546161, 2021). "However, in pathological complications such as preeclampsia (PE), the RAAS is dysregulated since the levels of renin, angiotensin I (Ang I) and angiotensin II (Ang II) are reduced." (PMID 38411777, 2024). "In the pathogenesis of preeclampsia, the activation of NLRP3 by DAMPs leads to an increased blood pressure through sympathetic nervous system activation, activation of the renin–angiotensin–aldosterone system (RAAS), tubulointerstitial inflammation, and placental abruption." (PMID 35563719, 2022). "The higher percentage of preeclampsia in this subgroup could be explained by the fact that all these patients also had CKD and that a possible intrarenal renin-angiotensin-aldosterone system (RAAS) could be involved." (PMID 32349458, 2020). "The interaction between renin and oxidised AGT, which is present in excess in the plasma of women with preeclampsia, is accelerated in the presence of s(P)RR, which is also increased in preeclampsia." (PMID 31551925, 2019). "Since (P)RR increases the catalytic activity of renin with oxidised AGT and levels of both s(P)RR and oxidised AGT are increased in preeclampsia, the increased release of s(P)RR could contribute to the dysregulation of maternal RASs in preeclampsia." (PMID 31551925, 2019). "Three haplotype-tagging SNPs (htSNPs) covering REN (rs5705, rs1464818, and rs3795575) and another three covering AGT (rs2148582, rs2478545 and rs943580) were genotyped in 99 mother-father-child triads of preeclampsia pregnancies." (PMID 20537141, 2010). "In normal pregnancy several findings support a predominance of the vasodilator effects of the renin-angiotensin-system, as opposed to an activation of its pressor actions in preeclampsia." (PMID 19646248, 2009). "The imbalance of the renin-angiotensin aldosterone system (RAAS) along with the imbalance between proangiogenic and anti-angiogenic factors may explain the relationship between preeclampsia and renal impairment." (PMID 36833689, 2023). "Also, the placental renin-angiotensin-aldosterone system (RAAS) may be a common factor connecting PAPP-A and sFlt-1 to the pathophysiology of preeclampsia." (PMID 23557166, 2013). "In preeclampsia PRA, plasma renin concentration and plasma Ang II are reduced compared to normal pregnancy." (PMID 19646248, 2009). "In contrast, the Stox1-KO phenotype was driven by endogenous upregulation of renin, which would not be expected to have as striking a phenotype because of the presence of intact blood pressure and RAS regulatory mechanisms, and is more consistent with human gestational hypertension." (PMID 33301424, 2021).
Myocardial fibrosis (68 papers, 2008 to 2025). "Concurrently, this process activates inflammatory responses and neurohumoral systems (e.g., the renin‐angiotensin‐aldosterone system), increasing LA wall stiffness and myocardial fibrosis, and predisposing to various atrial arrhythmias." (PMID 41328738, 2025). "Usually, patients with CKD have a profibrotic status because of increased accumulation of collagen in the connective tissue and activation of the renin–angiotensin–aldosterone system, which predispose individuals to myocardial fibrosis." (PMID 35453886, 2022). "Considering the role played by the local activation of the renin‐angiotensin system (RAS) in myocardial fibrosis, we then analysed the early (4 h) mRNA expression of Agtn, Ace and At1r in cells exposed to IS and pretreated with vehicle or CH." (PMID 38506079, 2024). "The activation of neurohormones in renin-angiotensin-aldosterone systems is a potent stimulator of myocardial fibrosis." (PMID 38521897, 2024). "The findings indicated that the anti-inflammatory effect of PGBR improved myocardial fibrosis by inhibiting genes involved in the renin–angiotensin system and fibrosis." (PMID 36613225, 2022). "GC-A receptor stimulation has natriuretic, vasodilatory, cardiorenal protective and anti-renin–angiotensin–aldosterone system actions, and GC-B receptor stimulation can suppress myocardial fibrosis and can activate bone growth before epiphyseal plate closure." (PMID 35741380, 2022). "Targeting Toll-like receptor 4 inflammatory pathways and renin-angiotensin system signaling to reduce myocardial fibrosis and abnormal cardiac remodeling following preterm birth warrants further investigation in humans." (PMID 34384550, 2021). "Myocardial fibrosis in end-stage heart failure is due to activation of the circulating renin-angiotensin system (RAS) and aldosterone production that eventually lead to progressive myocyte dysfunction, apoptosis, and fibroblast hyperplasia." (PMID 27840608, 2016). "Activation of the renin-angiotensin-aldosterone system (RAAS) has been shown to promote myocardial fibrosis and diastolic dysfunction." (PMID 24349097, 2013). "As a main active metabolite of renin-angiotensin system, Ang II plays a key role in promoting MH and myocardial fibrosis." (PMID 21876715, 2012). "The pathogenesis of myocardial dysfunction is multifaceted, but includes activation of renin-angiotensin aldosterone system, myocardial steatosis, autonomic dysfunction and increased myocardial fibrosis." (PMID 23217199, 2012). "Ang II, the main effector of the renin-angiotensin system, binds to the angiotensin type 1 receptor, leading to cardiac fibroblast proliferation, intercellular collagen overexpression, matrix deposition, and myocardial fibrosis." (PMID 38580957, 2024). "By directly or indirectly activating fibroblasts and promoting the expression of other related factors that affect collagen synthesis in fibroblasts, Gal-3 promotes myocardial fibrosis by interacting with the renin–angiotensin–aldosterone system and mediated by TGF-β and Hippo pathways." (PMID 36871006, 2023). "In recent years, studies have found that myocardial fibroblast activation, inflammatory response, transformed growth actor-β, renin-angiotensin-aldosterone system (RAAS) activation, and autophagy are closely associated with the occurrence and progression of myocardial fibrosis." (PMID 33582656, 2021). "Recovered patients may have persistently increased cardio metabolic demand, reduced cardiac reserve, myocardial fibrosis or scarring, and dysregulation of the renin–angiotensin–aldosterone system." (PMID 34827194, 2021). "Overactivation of the renin-angiotensin system has been shown in the rat model of hyperoxia exposure, whereby neonatal treatment with an angiotensin II type 1 receptor blocker prevents the development of myocardial fibrosis in adulthood." (PMID 34384550, 2021).
Myocardial fibrosis (continued). "The difference in disease severity between the two studies probably accounts for these findings since myocardial fibrosis may only be detectable in more advanced disease states as a result of the chronic activation of the renin-angiotensin-aldosterone system." (PMID 26187817, 2015). "NO synthase has been reported to attenuate myocardial fibrosis by regulating renin release." (PMID 24223630, 2013). "Blockade of the Renin- angiotensin system also reduces fibrosis both in animal models and human participants, by various actions such as growth factor inhibition and attenuation of inflammation Targeting AGEs holds promise in myocardial fibrosis and arterial stiffness." (PMID 37492439, 2023). "It was reported that NO synthase could attenuate myocardial fibrosis by regulating renin release." (PMID 21798071, 2011). "Another important factor is the renin-angiotensin-aldosterone system (RAAS) activation, which potentially induces myocardial fibrosis and hypertrophy." (PMID 37661275, 2023). "The renin-angiotensin-aldosterone system (RAAS), especially angiotensin II and aldosterone, play a key role in myocardial fibrosis." (PMID 29017565, 2017). "Activation of the local Renin–Angiolensin–Aodosterone System (RAAS), especially the concentration of AngII was greatly responsible for myocardial fibrosis." (PMID 24937684, 2014). "Clinical biomarkers of the renin-angiotensin-aldosterone (RAAS) system were not correlated with replacement myocardial fibrosis (P≥0.90)." (PMID 40395817, 2025). "The inhibition of the renin-angiotensin-aldosterone system, induced by angiotensin-converting enzyme inhibitors (ACEIs) and angiotensin II receptor blockers (ARBs), reduces myocardial fibrosis, regardless of its hypotensive action." (PMID 30917836, 2019). "There are some reports which have indicated that suppression of the renin-angiotensin-aldosterone system (RAAS) may prevent atrial fibrillation, mainly through the reduction of myocardial fibrosis." (PMID 18379655, 2008). "Here we show that the oral renin inhibitor aliskiren has direct effects on collagen metabolism in cardiac fibroblasts and prevented myocardial collagen deposition in a non-hypertrophic mouse model of myocardial fibrosis." (PMID 24349097, 2013).
anemia (62 papers, 2013 to 2025). A reduction in the number of red blood cells, the amount of hemoglobin, and/or the volume of packed red blood cells. "Numerous studies have also shown that anemia is associated with poor outcomes in patients with cardiovascular disease due to chronic inflammation, inhibition of the renin–angiotensin–aldosterone system, and renal dysfunction." (PMID 40822016, 2025). "Low HGB indicates anemia, which in liver disease is often accompanied by plasma volume expansion caused by splanchnic vasodilation and activation of the renin-angiotensin-aldosterone system, increasing the Vd of hydrophilic drugs such as TEIC." (PMID 41424785, 2025). "Regarding medications related to anemia development, inhibition of the renin-angiotensin system can lead to anemia, and the use of proton pump inhibitors is also linked to anemia." (PMID 37955878, 2024). "In the general population, renin-angiotensin system inhibitors are associated with a 50–60% higher risk of anaemia." (PMID 30290796, 2018). "Other drugs that have been associated with post-renal transplant anemia include inhibitors of the renin-angiotensin-aldosterone system (RAAS)." (PMID 24346775, 2013). "CKD promotes HF through volume overload, hypertension, anemia, activation of the renin–angiotensin–aldosterone system, sympathetic overactivity, systemic inflammation, and endothelial dysfunction." (PMID 41295373, 2025). "ADTKD-REN results from mutations in the REN gene encoding preprorenin, with clinical hallmarks including reduced glomerular filtration rate (GFR), hypotension, anemia and gout." (PMID 41480152, 2025). "CKD promotes HF through sodium and water retention, activation of the renin–angiotensin–aldosterone system, sympathetic overactivity, anemia, and systemic inflammation, all contributing to adverse cardiac remodeling and impaired function." (PMID 41295373, 2025). "Other effective measures, including the use of renin–angiotensin system inhibitors, addressing anemia, exercise therapy, and lifestyle improvements, have been reported." (PMID 38592226, 2024). "It appears that additional interstitial cells are recruited to express renin under certain conditions, for example, during anemia-induced hypotension or in experimental renal injury." (PMID 35511367, 2022). "The mechanisms underlying LVH are complex, and include chronic volume overload, arterial stiffness, elevated systolic blood pressure, anemia, activation of the renin–angiotensin and sympathetic nervous systems, and CKD-related mineral and bone disorders." (PMID 34442433, 2021). "Here we report that knockout mice that lack angiotensin II, including angiotensinogen and renin knockout mice, exhibit anemia." (PMID 26107632, 2015). "Furthermore, anemia leads to activation of the renin–angiotensin–aldosterone system as the kidneys sense a relative reduction in circulating blood volume." (PMID 41368299, 2025). "Meanwhile, anemia activates the sympathetic and renin–angiotensin–aldosterone systems, lowering vascular resistance while increasing cardiac output and heart rate; chronic anemia may further promote left ventricular remodeling and cardiomyocyte death." (PMID 41348379, 2025). "Preoperative anemia—due to malnutrition, chronic bleeding, or trauma—may increase cardiac workload by activating the sympathetic and renin–angiotensin systems, inducing ventricular remodeling and systolic dysfunction." (PMID 41458488, 2025). "Inhibition of the renin-angiotensin system could contribute to the development of anaemia through several means." (PMID 38463117, 2024). "With regard to the potential EPO-producing ability of renin-producing cells, one could speculate about new therapeutic opportunities to treat anemia in patients with chronic kidney disease." (PMID 35511367, 2022).